NDUFV1-DT (NDUFV1 divergent transcript)
Synonyms: C11orf72; FLJ90834
Gene: Long non-coding RNA gene on chromosome 11 (67,602,880 to 67,606,766, reverse strand). Ensembl gene ENSG00000184224.
Diseases named in the same sentence as NDUFV1-DT in open-access papers:
NDUFV1-DT is named in the same sentence as 2 diseases in open-access papers, as found by Europe PMC text mining. Sharing a sentence is not in itself a finding about the gene and the disease.
NDUFV1-DT shares sentences with these, for which no sentence is quoted: cancer (1 paper); metastatic tumor (1).